AURKB (aurora kinase B)
Diseases named in the same sentence as AURKB in open-access papers (continued):
Sharing a sentence is not in itself a finding about the gene and the disease.
cervical cancer (8 papers, 2012 to 2026). A primary or metastatic malignant neoplasm involving the cervix. "In our study, we found that AURKB up-regulation was associated with poor clinical prognosis in cervical cancer, suggesting that AURKB may play a vital role in cervical cancer, and thus may function as a potential therapeutic target for cervical cancer." (PMID 32258155, 2020). "In contrast to HPV-negative HNSC samples, HPV-positive tumors showed the same tendency as cervical cancers with respect to the expression of COL5A, MMP2, CLDN7, TAGLN, and AURKB, supporting their possible contribution to virus-induced carcinogenesis." (PMID 30918060, 2019). "After combination of the expression pattern and survival analysis, eight upregulated hub gens (CCNB1, BUB1, CDK1, AURKB, KIF11, PBK and NUSAP1) stood out with dramatical upregulation in cervical cancer and were significantly correlated with good prognosis of cervical cancer (P < 0.05)." (PMID 33682613, 2021). "Then, the top 40 hub genes were conducted to evaluate the expression and prognostic values of cervical cancer and 7 upregulated (BUB1, CCNB1, CDK1, AURKB, KIF11, PBK, NUSAP1) and 1 downregulated (ESR1) hub genes were selected to have significant values as biomarkers." (PMID 33682613, 2021). "Furthermore, inhibitor of aurora kinase B, ZM447439, suppresses the growth of cervical cancer SiHa cells and enhances the chemosensitivity to Cisplatin." (PMID 22283874, 2012). "However, the expression and role of AURKB in development and progression of cervical cancer have not been fully explored." (PMID 32258155, 2020). "Oncogenic kinases and methyltransferases including AURKA, AURKB, ESCO1, NEK6, and PRMTs that promote carcinogenesis are notably upregulated in cervical cancer." (PMID 41562705, 2026).
myeloma (8 papers, 2013 to 2025). "As described in this review, inhibitors of half of these (PLK1, TYK2 and AURKB) have been studied to one degree or another as potential targets in MM while the other three represent fertile ground for new anti-myeloma development." (PMID 27655636, 2016). "Our previous study demonstrated that as many as 5 of 17 genes found to be significantly up-regulated in ALDH1+ myeloma cells encode cell cycle-dependent protein kinases; specifically, CDC2, TTK, AURKA, AURKB and, of importance here, NEK2." (PMID 25230277, 2014). "In our study, AURKB was strongly expressed in SP cells from both myeloma cell lines and primary myeloma samples." (PMID 23469177, 2013). "Moreover, CCNB1, AURKB, EZH2 and PSMA5 were also upregulated in the SPs from eight primary myeloma samples." (PMID 23469177, 2013). "Expression of some genes connected with centrosome formation and function (AURKA, AURKB, CETN2, and PLK4) was significantly different between hyperdiploid and non-hyperdiploid myeloma patients." (PMID 23522059, 2013).
thyroid cancer (8 papers, 2019 to 2025). "AURKB facilitates chromosome segregation and cytokinesis, and its overexpression correlates with poor prognosis in breast, bladder, and thyroid cancers." (PMID 40416783, 2025). "For these studies, BRAF-mutant thyroid cancer cells were treated with vehicle, MEKi, the AURKB inhibitor, barasertib (AURKBi), or the combination, for 72 hrs and counted using automated counting." (PMID 38521968, 2024). "The levels of AURKB were also analyzed in normal cells (Nthy-ori 3-1) and thyroid cancer cell lines (CAL-62, B-CPAP, and TPC-1)." (PMID 38441546, 2024). "Here, we identified an induction of Aurora kinase B (AURKB) in response to MEKi in BRAF-mutant thyroid cancer cells that are resistant to combined BRAF/MEK1/2 inhibition." (PMID 38521968, 2024). "Overall, our findings supported the notion that the interplay between GSG2 and AURKB actively contributes to the development of thyroid cancer." (PMID 38441546, 2024). "Together, these data suggest inhibition of AURKB in combination with a MAPK-directed therapy is a promising target for BRAF-mutant thyroid cancer." (PMID 38521968, 2024). "By targeting both cell growth and division, combined inhibition of MAPK signaling and AURKB represents an attractive therapeutic alternative for patients with advanced thyroid cancer." (PMID 38521968, 2024). "On the other hand, we unraveled the molecular mechanism behind GSG2 regulating thyroid cancer, identifying AURKB as a downstream gene of GSG2." (PMID 38441546, 2024). "The results revealed a significant increase in AURKB at the protein and mRNA levels in thyroid cancer cell lines compared to Nthy-ori 3-1 cells." (PMID 38441546, 2024). "AURKB has been shown to be highly expressed in thyroid cancer and has value as a potential target marker for renal cell carcinoma." (PMID 32379058, 2020). "The block of AURKB expression or by using an inhibitor of Aurora kinase activity significantly reduced the growth of thyroid carcinoma cells." (PMID 32626756, 2020). "Further experiments indicated that silencing AURKB can obviously inhibit the growth of thyroid carcinoma cells." (PMID 31576249, 2019). "We hypothesized that AURKB inhibition will sensitize BRAF-mutant thyroid cancer cells to inhibition of the MAPK pathway." (PMID 38521968, 2024). "Furthermore, overexpressing AURKB restored the functional consequences of GSG2 depletion in thyroid cancer cells." (PMID 38441546, 2024). "In our pursuit to comprehend the impact of GSG2 on thyroid cancer cells and ascertain whether these changes were orchestrated by AURKB, we conducted experiments." (PMID 38441546, 2024). "Hence, they thought that AURKB was an important protein in the progression of thyroid carcinomas and a promising candidate for targeted treatment." (PMID 31576249, 2019). "Overall, combined AURKB and MEK1/2 inhibition decreases cell growth 64–87%, suggesting a potential benefit of combined MEK1/2 and AURKB inhibition in BRAF-mutant thyroid cancer cell lines." (PMID 38521968, 2024). "GSG2 knockdown significantly increased the ubiquitination level of AURKB, providing additional insights into the regulatory mechanisms of GSG2-mediated thyroid cancer." (PMID 38441546, 2024). "Finally, we show that combined AURKB and ERK1/2 inhibition induces apoptosis in BRAF-mutant thyroid cancer cell lines, together suggesting a potential combination therapy for BRAF-mutant thyroid cancer patients." (PMID 38521968, 2024). "It is interesting to note that inhibition of AURKB and ERK1/2, as opposed to other nodes of the MAPK pathway, most robustly inhibited growth in BRAFV600E mutant thyroid cancer cell lines." (PMID 38521968, 2024).
liver cancer (7 papers, 2010 to 2025). An epithelial or non-epithelial malignant neoplasm that arises from the liver. "Demonstrating that AURKB has been shown to be closely associated with liver cancer, its upregulation plays a key role in promoting hyper polyploidization, and an increase in AURKB phosphorylation was detected on intermediates during cytokinesis, leading to hyperpolyploidization." (PMID 36120466, 2022). "The involvement of polyploidization and subsequent ploidy reduction in hepatocarcinogenesis was further suggested by the modulation of aurora kinase B (Aurkb), which plays a role in hepatocyte polyploidization and liver cancer development." (PMID 36012671, 2022). "The expression of AURKB was increased in patients of certain races, and AURKB may be used as a biomarker for the detection of liver cancer in different regions." (PMID 38396874, 2024).
lymphoma (7 papers, 2008 to 2025). A malignant (clonal) proliferation of B- lymphocytes or T- lymphocytes which involves the lymph nodes, bone marrow and/or extranodal sites. "(ii) BIRC5 (baculoviral IAP repeat-containing 5 gene), an inhibitor of apoptosis (IAP gene family) is expressed in most tumours and in lymphoma, participates in the spindle checkpoint and associates with AURKB." (PMID 18416826, 2008). "Inhibition of AURKB decreases the expression of Cyclin B1 and Cyclin D1, and elevates the Caspase 3 expression in lymphoma cells." (PMID 28147341, 2017). "In consistence with Guise AJ group, it has been shown that AURKB and HDACs synergistically regulate cell survival and proliferation in lymphoma via activating AKT/mTOR signaling pathway." (PMID 28147341, 2017). "Interestingly, BUB1 overexpression induces aneuploidy in lymphoma cells through Aurora B kinase (AURKB) hyperactivation, while BUB1 downregulation occurs in a subset of acute myeloid leukemia." (PMID 32781708, 2020). "Median expression levels were invariably higher for AURKB, BCAT1, BIRC5, BUB1B, PBK and RACGAP1 and lower for FOSB, MAP3K1 and RIN3 by qPCR in lymphoma versus normal B cell samples in both species." (PMID 24130802, 2013).
small cell lung carcinoma (7 papers, 2017 to 2026). Small cell lung cancer (SCLC) is a highly aggressive malignant neoplasm, accounting for 10-15% of lung cancer cases, characterized byrapid growth, and early metastasis. "AZD2811 is an AURKB inhibitor that demonstrated tolerability during a Phase I dose-escalation study in patients with advanced solid tumours, including small-cell lung cancer (SCLC)." (PMID 41933194, 2026). "The BCL2 gene contributes to the resistance of small cell lung cancer (SCLC) to Aurora kinase B (AURKB) inhibitors." (PMID 41378310, 2025). "Previous studies have highlighted RB1-dependent sensitivity to AURKA/B inhibitors and also identified AURKB as a synthetic lethal dependency in RB1-defective small cell lung cancers (SCLC)." (PMID 40138429, 2025). "AURKB is targetable by the kinase inhibitor barasertib, found to be effective in combating small-cell lung cancer in vitro and in xenografts." (PMID 29149186, 2017). "Several AURKB inhibitors have been investigated in phase 1–2 clinical trials, with success in some solid tumours, especially those with rapid cell turnover and dependency on efficient mitoses, such as small cell lung cancer (SCLC)." (PMID 36871042, 2023).
COVID-19 (6 papers, 2021 to 2024). A disease caused by infection with severe acute respiratory syndrome coronavirus 2. "The gene AURKB plays a crucial role as a biomarker gene in the diagnosis and prognosis of COVID-19 patients." (PMID 36913345, 2023). "It was then remarkable to find that the AURKB inhibitor Barasertib with strong negative correlations across the temporal meta-signatures and is in COVID-19 clinical trials." (PMID 38107402, 2023). "Many of the cell cycle-related genes, such as aurora kinase B (AURKB) and cyclin-dependent kinase inhibitor 1A (CDKN1A, p21), were consistently upregulated in a COVID-19 specific manner, while some were consistently downregulated, such as cyclin-dependent kinase inhibitor 1C (CDKN1C, p57)." (PMID 35991542, 2022).
head and neck squamous cell carcinoma (6 papers, 2015 to 2025). A squamous cell carcinoma that arises from any of the following anatomic sites: lip and oral cavity, nasal cavity, paranasal sinuses, pharynx, larynx, and salivary glands. "Notably, aurora kinase B (AURKB) is overexpressed in 40–60 % of HPV-associated cancers, as demonstrated in cervical and head and neck squamous cell carcinoma." (PMID 40508156, 2025). "Overexpression and hyperactivation of AURKA and AURKB have major roles in tumorigenesis, and therefore their inhibitors are already regarded as promising therapeutics for various types of cancer, including head and neck squamous-cell carcinoma." (PMID 25936657, 2015). "Previous studies have indicated that inhibition of AURKB can enhance radiosensitivity in androgen blockade-resistant prostate cancer 29 and suppresses the growth of cetuximab-resistant head and neck squamous cell carcinoma (HNSCC) cells." (PMID 32863956, 2020).
prostate tumors (6 papers, 2014 to 2024). "Because of the lethality associated with AURKB defects, our focus was solely on investigating NSFL1C, and our findings revealed that its loss could promote the growth of prostate tumors with BRCA2 deficiency." (PMID 37934606, 2024). "Aurora Kinase B (AURKB) is a serine/threonine kinase,which is known for its effect as a central regulator of chromosome separation and cytokinesis, and is overexpressed in some tumors, such as lung, breast, pancreatic, ovarian, and prostate tumors." (PMID 37318676, 2023).
renal cell carcinoma (5 papers, 2020 to 2024). "AURKB expression is up-regulated in renal cell carcinoma and positively correlated with the expression of ALKBH5." (PMID 38396874, 2024). "ALKBH5 stabilizes AURKB mRNA in an m6A-dependent manner, thereby promoting the development of renal cell carcinoma." (PMID 38396874, 2024). "This is consistent with the observation in renal cell carcinoma where ALKBH5 directly binds to AURKB mRNA in an m6A-dependent manner, enhancing the stability of the AURKB transcript and promoting its expression, ultimately leading to cell proliferation." (PMID 33926508, 2021).
astrocytoma (4 papers, 2011 to 2022). "The expression of SIX3, AURKA, and AURKB were further studied in 18 human astrocytoma samples, and both AURKA and AURKB expression showed an inverse relationship with the expression of SIX3." (PMID 28595628, 2017). "SIX3 is a novel negative transcriptional regulator and acts as a tumor suppressor that directly represses the transcription of AURKA and AURKB in astrocytoma." (PMID 28595628, 2017). "SIX3 is identified as a novel negative transcriptional regulator of AURKA and AURKB, and it decreases the expression of AURKA and AURKB in a dose-dependent manner in astrocytoma cells." (PMID 28595628, 2017). "SIX3 silencing results in high expression of AURKA and AURKB in astrocytoma." (PMID 28595628, 2017). "A strong inverse correlation between SIX3 and AURKA/AURKB were obtained with normal astrocyte cell line HEB and three astrocytoma cell lines by Western blotting." (PMID 28595628, 2017). "Three primary human patient-derived astrocytoma lines were cultured, and the expression of SIX3, AURKA, and AURKB was examined." (PMID 28595628, 2017). "We found that high SIX3 expression in astrocytoma resulted in low sensitivity to aurora kinase inhibitors, and this may partially be due to low expression of AURKA and AURKB." (PMID 28595628, 2017). "We demonstrate that in astrocytoma, SIX3 acts as a tumor suppressor gene by transcriptionally repressing AURKA and AURKB but does not affect the interaction of AURKA and AURKB." (PMID 28595628, 2017). "Since SIX3 has been confirmed as a negative transcriptional regulator of AURKA and AURKB, we wondered whether SIX3 expression is correlated with the sensitivity of astrocytoma cells to aurora kinase inhibitors." (PMID 28595628, 2017).
chronic myeloid leukemia (4 papers, 2019 to 2025). "In the context of resistance to TKIs, an AURKA/AURKB inhibitor has been reported to induce senescence in chronic myeloid leukemia cells carrying the imatinib-resistant T315I mutation in ABL50." (PMID 31000705, 2019). "In chronic myeloid leukemia (CML), the BCR-ABL oncoprotein upregulates AURKA and AURKB via the Akt signaling pathway, promoting leukemogenesis." (PMID 41296411, 2025). "Is it possible to eliminate metastasised chronic myeloid leukaemia (CML) and acute myeloid leukaemia (AML) cells from ovarian cortex fragments by inhibition of Aurora B/C kinases (AURKB/C) without compromising ovarian tissue or follicles?" (PMID 33725274, 2021).
neutropenia (4 papers, 2015 to 2023). A decrease in the number of neutrophils found in the blood. "Based on the key role of AURKB in mitosis, neutropenia and decreased neutrophil count are expected toxicities of treatment with AURKB inhibitors due to the rapid rate of cell division in bone marrow neutrophils." (PMID 36871042, 2023). "This behavior is not influenced by the AURK isoform selectivity of the inhibitors as neutropenias were induced by both AURKA and AURKB selective inhibitors." (PMID 36224199, 2022).
psoriasis (4 papers, 2022 to 2024). An autoimmune condition characterized by red, well-delineated plaques with silvery scales that are usually on the extensor surfaces and scalp. "Elevated AURKB expression in lesional psoriatic tissues has been suggested to contribute to the development of psoriasis." (PMID 36699197, 2022).
adenoma (3 papers, 2013 to 2025). A neoplasm arising from the epithelium. "ScRNA-seq analysis revealed that AURKB was predominantly expressed in the epithelial cells, particularly within adenoma and tumor regions." (PMID 40784984, 2025). "Some genes or gene families we found up-regulated in MENX adenomas had previously been identified in human aggressive-invasive PAs, e.g., PTTG1, RACGAP1, CCNB1, CENPE, AURKB." (PMID 23756599, 2013). "More specifically, genes with such a therapeutic potential in non-functioning adenomas included CACNA2D4, IDH1, AURKB, GRIA2, PTGS2 and CX3CR1." (PMID 33168897, 2020).
asthenozoospermia (3 papers, 2019 to 2022). "In asthenozoospermia, over-expression of AURKB might be associated with development of asthenozoospermia." (PMID 31576249, 2019). "Let‐7b‐5p was reported to target AURKB in asthenozoospermia, although, it is the role needs further validation in cancer." (PMID 34981672, 2022). "Over-expression of AURKB can decrease glycolytic activities, conferring to the occurrence and progression of asthenozoospermia." (PMID 31576249, 2019).
B-cell non-Hodgkin lymphoma (3 papers, 2015 to 2024). The most common type of non-Hodgkin lymphoma. "An additional highly ranked combination was the aurora kinase B inhibitor (AurkB) AZD2811 + venetoclax in B-cell non-Hodgkin lymphoma (NHL)." (PMID 38456804, 2024). "It was shown to inhibit AURKB activity, induce endoreduplication, suppress cell proliferation and enhance apoptosis in B-cell non-Hodgkin’s lymphoma cell lines." (PMID 33915740, 2021). "AT9283 suppresses tumor growth in aggressive B-cell lymphomas and in these cells, it had a potent anti-AURKB activity." (PMID 33915740, 2021).
cutaneous melanoma (3 papers, 2023 to 2025). A primary melanoma arising from atypical melanocytes in the skin. "This oncogenic pseudogene exhibits dysregulation in cutaneous melanoma, functioning as a competing endogenous RNA (ceRNA) to upregulate the oncogene AURKB." (PMID 41378127, 2025). "MTND4P12 is considered as an oncogenic pseudogene upregulated in skin cutaneous melanoma, and it can upregulate the expression of oncogene AURKB by serving as ceRNA34." (PMID 37258695, 2023).
esophageal cancer (3 papers, 2011 to 2024). A primary or metastatic malignant neoplasm involving the esophagus. "Additionally, GSEA enrichments revealed the suppression of cell cycle and mitotic checkpoint regulatory (AURKB, PLK1, and E2F) and the DDR and DNA-repair (ATR, BARD1, and FANCONI) pathways by STL001 in esophageal cancer." (PMID 38697979, 2024).
Ewing sarcoma (3 papers, 2010 to 2021). A small round cell tumor that lacks morphologic, immunohistochemical, and electron microscopic evidence of neuroectodermal differentiation. "In some other studies, kinases such as JNK, TOPK, AURKA, AURKB and LYN have all been studied in Ewing's sarcoma." (PMID 20718987, 2010).
lymph node metastasis (3 papers, 2014 to 2023). "We also analyzed the correlation between AURKB expression and clinicopathological parameters in 103 patients and found that AURKB expression was associated with serum CA19-9 level, tumor number, and lymph node metastasis." (PMID 37318676, 2023). "It was found that AURKB expression was correlated with serum CA19-9 level (P = 0.006), tumor number (P = 0.008), and lymph node metastasis (P = 0.023)." (PMID 37318676, 2023).